WASH9P (WAS protein family homolog 9, pseudogene)
Gene: Transcribed unprocessed pseudogene on chromosome 1 (185,217 to 195,411, reverse strand). Ensembl gene ENSG00000279457.
Diseases named in the same sentence as WASH9P in open-access papers:
WASH9P is named in the same sentence as 1 disease in open-access papers, as found by Europe PMC text mining. Sharing a sentence is not in itself a finding about the gene and the disease. The quoted sentences say what the papers report.
preeclampsia (1 paper, 2022). Preeclampsia is a hypertensive disorder of pregnancy that is characterized by new-onset hypertension with proteinuria presenting after 20 weeks of gestation, and depending on mild or severe forms may initially present with severe headache, visual disturbances, and hyperreflexia. "We developed a 5-mRNA signature (termed PE5-signature) to diagnose preeclampsia from 38 DEGs using recursive feature elimination with a random forest supervised classification algorithm, including ENG, KRT80, CEBPA, RDH13 and WASH9P." (PMID 35774506, 2022).